PELI3 (pellino E3 ubiquitin protein ligase family member 3)
Description:
E3 ubiquitin ligase catalyzing the covalent attachment of ubiquitin moieties onto substrate proteins. Involved in the TLR and IL-1 signaling pathways via interaction with the complex containing IRAK kinases and TRAF6. Mediates 'Lys-63'-linked polyubiquitination of IRAK1. Can activate AP1/JUN and ELK1. Acts as a regulator of innate immunity by mediating 'Lys-63'-linked polyubiquitination of RIPK2 downstream of NOD1 and NOD2, thereby transforming RIPK2 into a scaffolding protein for downstream effectors, ultimately leading to activation of the NF-kappa-B and MAP kinases signaling (By similarity). Catalyzes 'Lys-63'-linked polyubiquitination of RIPK2 in parallel of XIAP (By similarity).
Synonyms: MGC35521
Tractability: PROTAC: ubiquitination databases record sites on it.
Gene: Protein-coding gene on chromosome 11 (66,466,303 to 66,478,998, forward strand). Ensembl gene ENSG00000174516.
Subcellular location (Human Protein Atlas): Nucleoplasm; Vesicles; Nucleoli
Pathways (Reactome):
Immune System: IRAK1 recruits IKK complex; IRAK1 recruits IKK complex upon TLR7/8 or 9 stimulation; Interleukin-1 signaling
Gene Ontology:
Molecular function: protein binding; ubiquitin protein ligase activity
Biological process: negative regulation of extrinsic apoptotic signaling pathway; negative regulation of tumor necrosis factor-mediated signaling pathway; protein K63-linked ubiquitination; protein polyubiquitination; protein ubiquitination; regulation of Toll signaling pathway
Cellular component: cytosol
Genetic constraint (gnomAD): Loss-of-function variants: 20 observed, 39.29 expected, observed/expected ratio (o/e) 0.51, 90% interval 0.36 to 0.74. The upper end of that interval is the gene's LOEUF score, 0.74, which puts it in group 3 of 6, group 1 being the genes least tolerant of losing a copy. Missense variants: 473 observed, 641.65 expected, observed/expected ratio (o/e) 0.74, 90% interval 0.68 to 0.8. Synonymous variants: 257 observed, 275.7 expected, observed/expected ratio (o/e) 0.93, 90% interval 0.84 to 1.03.
Homologues: Orthologues: chimpanzee PELI3 (99% identical), macaque PELI3 (99% identical), pig PELI3 (99% identical), rabbit PELI3 (97% identical), guinea pig PELI3 (93% identical), dog PELI3 (93% identical), rat Peli3 (92% identical), mouse Peli3 (92% identical), zebrafish peli3 (72% identical), Drosophila melanogaster Pli (48% identical), Caenorhabditis elegans peli-1 (39% identical). Paralogues in human: PELI2 (63% identical), PELI1 (63% identical).
Diseases named in the same sentence as PELI3 in open-access papers:
PELI3 is named in the same sentence as 21 diseases in open-access papers, as found by Europe PMC text mining. Sharing a sentence is not in itself a finding about the gene and the disease. The quoted sentences say what the papers report.
non-small cell lung carcinoma (3 papers, 2019 to 2025). A group of at least three distinct histological types of lung cancer, including non-small cell squamous cell carcinoma, adenocarcinoma, and large cell carcinoma. "miR-365a-5p inhibits the viability, colony formation, migration, and invasion of non-small cell lung cancer cells by negatively regulating Pellino E3 ubiquitin protein ligase family member 3 (PELI3), and PELI3 silencing promotes the miR-365a-5p-mediated suppression of pro-tumoral effects." (PMID 33023466, 2020).
Insulin resistance (2 papers, 2019 to 2021). Increased resistance towards insulin, that is, diminished effectiveness of insulin in reducing blood glucose levels. "PELI3 was an important member in the Pellino E3 ubiquitin protein ligase family and recently received attentions in the inflammatory response and insulin resistance." (PMID 30995936, 2019).
Obesity (2 papers, 2017 to 2018). Accumulation of substantial excess body fat. "TLR signaling is known to promote obesity-induced resistance to insulin and leptin, suggesting that upregulation of Peli3 in response to HFD is implicated in the increased serum concentrations of insulin and leptin observed in the present study." (PMID 28170448, 2017). "We found that several serum leptin-associated genes including Peli3, Creb1, and Enpp2 and serum insulin-associated genes such as Centg1 are associated with obesity and colonic diseases." (PMID 28170448, 2017). "Our data suggest Peli3, Creb1, Enpp2, and Centg1 as potential early biomarker candidates for obesity-induced pathophysiological changes in the colon." (PMID 28170448, 2017). "Taken together, these results indicate that Peli3 could be a potential early biomarker of obesity-induced colonic diseases." (PMID 28170448, 2017).
adenoma (1 paper, 2023). A neoplasm arising from the epithelium. "Histologically, these tumours were diagnosed as well differentiated adenocarcinoma in WT mice with sub‐mucosal invasion, whereas tumours from Peli3 KO mice were small tubular non‐invasive adenomas." (PMID 37341064, 2023).
colitis (1 paper, 2023). Inflammation of the colon. "To investigate the novel biological roles of Peli3 in colitis‐associated tumour development, we generated whole Peli3 KO mice by crossing with a β‐actin Cre driver mouse." (PMID 37341064, 2023). "Because Peli3 is involved in the development of ACF at the early stages of colon cancer, we assessed the function of Peli3 in colitis‐induced inflammation." (PMID 37341064, 2023). "For this purpose, age‐matched Peli3 WT and KO mice were chosen to create a DSS‐induced acute colitis model." (PMID 37341064, 2023).
colon cancer (1 paper, 2023). "By modulating these negative signals in inflammation, Peli3 may functions as an oncogene of colon cancer, especially working at the cancer microenvironment." (PMID 37341064, 2023).
colonic tumours (1 paper, 2023). "In three independent experiments, the incidence of colonic tumours was observed in both WT and Peli3 KO mice and were most frequently observed in the middle and distal colon." (PMID 37341064, 2023).
tumor (4 papers, 2019 to 2025). "The xenograft tumor size was significantly decreased in PELI3-deficient group in comparison with control and tumor growth was greatly retarded by PELI3 knockdown during the experimental window." (PMID 30995936, 2019). "We observed that Peli3 promotes colorectal tumorigenesis, with increased tumour burden and inflammatory signalling pathways." (PMID 37341064, 2023). "We observed that Peli3 promotes colorectal carcinogenesis with increased tumour burden and oncogenic signalling pathways." (PMID 37341064, 2023). "Activation of NF‐κB, STAT3 and ERK signalling pathways were also highly induced in tumour tissues of Peli3 WT mouse compared to those in KO mouse." (PMID 37341064, 2023). "Here our results for the first time identified that PELI3 as the direct target of miR-365a-5p, which consequently contributed to its anti-tumor properties." (PMID 30995936, 2019). "The in vivo transcripts of PELI3 in clinical samples were also shown much higher in tumor than in normal control." (PMID 30995936, 2019). "More importantly, PELI3-deficiency significantly inhibited cell proliferation, migration and invasion provoked by the miR-365a-5p inhibition, which highlighted the dominant role of PELI3 in mediating the anti-tumor activity of miR-365a-5p in NSCLC." (PMID 30995936, 2019). "Drug distribution, metabolic stability, and tumor microenvironmental factors may influence Mebendazole’s ability to modulate the PELI3/TRADD axis in living systems." (PMID 41584581, 2025). "Interestingly, ablation of Peli3 led to significantly less number of tumour incidence than in WT mice." (PMID 37341064, 2023). "Moreover, the number of proliferating cells was significantly reduced in Peli3 KO tumour tissues compared with those in WT mice." (PMID 37341064, 2023). "Our data suggested the anti-tumor activity of miR-365a-5p via antagonism with PELI3." (PMID 30995936, 2019). "We first determined the relative expression of PELI3 in NSCLC clinical tissue samples; the significantly intensive signal was detected in the tumor samples in comparison with the benign control." (PMID 30995936, 2019).
colorectal (2 papers, 2023 to 2025). "For example, PELI1 activates the PI3 K/Akt/GSK3β signaling pathway, leading to poor prognosis of patients, and PELI3 promotes colorectal carcinogenesis through TLR4-mediated inflammation." (PMID 40500708, 2025).
infection (2 papers, 2014 to 2021). The state of being infected such as from the introduction of a foreign agent such as serum, vaccine, antigenic substance or organism. "Bioassay and ELISA results showed that the productions of biologically active type I interferon and other tested cytokines after infection with VSV are reduced in Peli3−/− BMDMs." (PMID 34306313, 2021).
colon (1 paper, 2023). "Then, Peli3 WT and KO mice were applied to the chemical‐induced colon carcinogenesis protocol." (PMID 37341064, 2023).
PELI3 also shares sentences with these, for which no sentence is quoted: adenocarcinoma (1 paper); breast carcinoma (1); cancer (1); cholangitis (1); colonic diseases (1); Crohn disease (1); injury (1); lung carcinoma (1); multiple sclerosis (1); viral infection (1).